HENMT1 (HEN methyltransferase 1)
Description:
Methyltransferase that adds a 2'-O-methyl group at the 3'-end of piRNAs, a class of 24 to 30 nucleotide RNAs that are generated by a Dicer-independent mechanism and are primarily derived from transposons and other repeated sequence elements. This probably protects the 3'-end of piRNAs from uridylation activity and subsequent degradation. Stabilization of piRNAs is essential for gametogenesis.
Synonyms: C1orf59; FLJ30525; HEN1
Tractability: Small molecule: a structure with a bound ligand is known. Antibody: the Human Protein Atlas places it where antibodies can reach. PROTAC: ubiquitination databases record sites on it.
Gene: Protein-coding gene on chromosome 1 (108,648,285 to 108,661,526, reverse strand). Ensembl gene ENSG00000162639.
Subcellular location: Cytoplasm
Subcellular location (Human Protein Atlas): Focal adhesion sites; Plasma membrane
Pathways (Reactome):
Gene expression (Transcription): PIWI-interacting RNA (piRNA) biogenesis
Gene Ontology:
Molecular function: protein binding; small RNA 2'-O-methyltransferase activity; O-methyltransferase activity; RNA methyltransferase activity
Biological process: piRNA processing; RNA methylation
Cellular component: cytoplasm; P granule
Genetic constraint (gnomAD): Loss-of-function variants: 20 observed, 17.26 expected, observed/expected ratio (o/e) 1.16, 90% interval 0.81 to 1.67. The upper end of that interval is the gene's LOEUF score, 1.67, which puts it in group 6 of 6, group 1 being the genes least tolerant of losing a copy. Missense variants: 364 observed, 411.67 expected, observed/expected ratio (o/e) 0.88, 90% interval 0.81 to 0.96. Synonymous variants: 142 observed, 151.57 expected, observed/expected ratio (o/e) 0.94, 90% interval 0.82 to 1.08.
Homologues: Orthologues: chimpanzee HENMT1 (100% identical), macaque HENMT1 (96% identical), guinea pig HENMT1 (71% identical), rat Henmt1 (70% identical), mouse Henmt1 (69% identical), rabbit HENMT1 (62% identical), pig HENMT1 (58% identical), dog HENMT1 (56% identical), tropical clawed frog henmt1 (39% identical), zebrafish henmt1 (38% identical), Drosophila melanogaster Hen1 (26% identical), Caenorhabditis elegans henn-1 (23% identical).
Diseases named in the same sentence as HENMT1 in open-access papers:
HENMT1 is named in the same sentence as 17 diseases in open-access papers, as found by Europe PMC text mining. Sharing a sentence is not in itself a finding about the gene and the disease. The quoted sentences say what the papers report.
breast carcinoma (3 papers, 2013 to 2022). "The transcription factors (TFs) NHLH1 and HENMT1 showed 50% abundance with known breast cancer genes." (PMID 33593445, 2021).
cervical cancer (2 papers, 2021 to 2022). A primary or metastatic malignant neoplasm involving the cervix. "As a low-risk gene, HENMT1 may be a marker for predicting the prognosis of cervical cancer patients." (PMID 35449547, 2022). "In this study, the expression of HENMT1 in cervical cancer patients is up-regulated, and its high expression indicates a better prognosis." (PMID 35449547, 2022). "Statistical analysis showed that the expression of HENMT1 in cervical cancer was higher than that in adjacent tissues." (PMID 35449547, 2022). "Finally, protein expression levels of RNASEH2A and HENMT1 in cervical cancer and adjacent tissues were verified by immunohistochemistry." (PMID 35449547, 2022). "Nonetheless, higher expression level of HENMT1, RBM38 and RNASEH2A showed a better overall survival of cervical cancer patients." (PMID 34863153, 2021).
Azoospermia (1 paper, 2024). Absence of any measurable level of sperm,whereby spermatozoa cannot be observed even after centrifugation of the semen pellet. "The homozygous variant c.400A>T p.(Ile134Leu) in HENMT1 was identified in M3079 affected by azoospermia due to round spermatid arrest." (PMID 39122675, 2024).
colon adenocarcinoma (1 paper, 2024). "Notably, HENMT1, the enzyme responsible for modifying the 3′-end of piRNAs, has been reported as one of the most highly dysregulated RNA modifying proteins in cancer including AML and colon adenocarcinoma." (PMID 39188528, 2024).
gastric adenocarcinoma (1 paper, 2024). "Three of those, HENMT1, GRIN2A, and STC2, seem to relate to processes such as hypoxia response and hormone-metabolism regulation, thereby contributing to the development and progression of several carcinomas, including gastric adenocarcinomas." (PMID 38542354, 2024).
leukemia (1 paper, 2020). A malignant (clonal) hematologic disorder, involving hematopoietic stem cells and characterized by the presence of primitive or atypical myeloid or lymphoid cells in the bone marrow and the blood. "While FTO has been shown to play an important role in leukemia, it is possible that additional RMPs such as HENMT1, which is drastically dysregulated in this cancer type, might constitute a better drug target to inhibit leukemogenesis." (PMID 32375858, 2020).
lung carcinoma (1 paper, 2022). "Methyltransferase HENMT1 inhibits apoptosis of lung cancer cells by enhancing its stability by 2′-O-methylation of the 3′-terminal of Mir-21-5p." (PMID 35790714, 2022).
male infertility (1 paper, 2015). The inability of the male to effect fertilization of an ovum after a specified period of unprotected intercourse. "Collectively, this study establishes HENMT1 and piRNA function as absolute requirements for male adult germ cell development and fertility and raises some interesting questions into the causality and treatment of human male infertility." (PMID 26496356, 2015).
non-small cell lung carcinoma (1 paper, 2024). A group of at least three distinct histological types of lung cancer, including non-small cell squamous cell carcinoma, adenocarcinoma, and large cell carcinoma. "Recently, HENMT1 was shown to be responsible for the methylation of the 3’-terminal 2’-Ome of mammalian miR-21-5p (see “micro RNA” section in S1 File.pdf), which plays a predominant role in human non-small cell lung cancer (NSCLC)." (PMID 38198468, 2024).
ovarian carcinoma (1 paper, 2022). A malignant neoplasm originating from the surface ovarian epithelium. "The expression of HENMT1 in ovarian cancer is increased with the increase of tumor grade, which was related to the degree of malignancy." (PMID 35449547, 2022).
cancer (7 papers, 2020 to 2024). A tumor composed of atypical neoplastic, often pleomorphic cells that invade other tissues. "Future work will be needed to decipher the biological role of LAGE3 and HENMT1 in cancer, as well as its potential use as a target for diagnostic and prognostic purposes." (PMID 32375858, 2020). "Based on this and our own results regarding the catalytic activity of HENMT1, we assume HENMT1 plays a role in proliferation of cancer cell lines derived from many different tissues." (PMID 38198468, 2024). "In the HENMT1 immunohistochemical expression micro array, after deleting the tissue points shed during the experiment, the expression of HENMT1 in the remaining 93 pairs of cancer and adjacent tissues was statistically analyzed." (PMID 35449547, 2022). "At the same time, RNASEH2A and HENMT1 were positively correlated with the expression of clinical markers (MKI67) in cancer tissues." (PMID 35449547, 2022). "Here, we attempted to validate the upregulation of LAGE3 and HENMT1 across a battery of 12 cancer types using tissue microarrays (TMAs)." (PMID 32375858, 2020). "Nevertheless, our results suggest that LAGE3 and HENMT1 have altered expression levels in specific cancer types also at the protein level." (PMID 32375858, 2020). "Surprisingly, we find that several commonly studied RNA modification enzymes such as METTL3 or FTO are not significantly upregulated in most cancer types, whereas several less-characterized RMPs, such as LAGE3 and HENMT1, are dysregulated in many cancers." (PMID 32375858, 2020). "Although the function of mammalian (mostly mouse) HENMT1 has been firmly established in fertility, there are recent reports that HENMT1 may also play an important role in some types of cancer." (PMID 38198468, 2024). "Whether the global upregulation of HENMT1 in cancer samples might be contributing to increased TE mutagenesis is currently unknown." (PMID 32375858, 2020). "Moreover, we identify two enzymes, LAGE3 and HENMT1, as the top recurrently upregulated RMPs across cancer types." (PMID 32375858, 2020). "Implications of aberrant HENMT1 expression in cancer are unknown but it has known roles in maintaining piRNA stability by 2′-O-methylation of piRNAs and ensuring TE repression." (PMID 33374923, 2020). "In cancer, 27% of all known human RMPs are dysregulated, among them HENMT1 and LAGE3 have been reported to be the two most frequently overexpressed genes across a wide variety of cancer types." (PMID 38198468, 2024). "Our comprehensive analysis revealed a more differentiated pattern where PIWIL1, MAEL and HENMT1 had increased expression, while PIWIL2, PIWIL4 and TDRD1 had decreased expression when comparing benign and malignant tumor samples." (PMID 33374923, 2020).
tumor (2 papers, 2020 to 2022). "At the same time, compared with the diagnostic efficiency of simple tumor markers, HENMT1 and RNASEH2A combined with clinical markers (MKI67) have higher diagnostic efficiency and reduce the misdiagnosis and missed diagnosis rate of patients to a certain extent." (PMID 35449547, 2022). "GEPIA database analysis showed that RNASEH2A and HENMT1 were positively correlated with the expression of tumor marker (MKI67)." (PMID 35449547, 2022). "RNASEH2A and HENMT1 are up-regulated in tumors, which can effectively distinguish normal tissues from tumor tissues." (PMID 35449547, 2022). "Finally, in order to explore the correlation between the markers predicted in this study and clinical tumor markers, the correlation between the experimental results of HENMT1, RNASEH2A and clinical tumor markers was analyzed." (PMID 35449547, 2022). "It was found that HENMT1 and RNASEH2A were positively correlated with the expression of tumor marker (MKI67)." (PMID 35449547, 2022).
benign tumors (1 paper, 2020). "RNA methyltransferase HENMT1 and spindle class gene MAEL both had significantly increased expression in HGSOC tumors compared to benign tumors." (PMID 33374923, 2020).
HENMT1 also shares sentences with these, for which no sentence is quoted: head and neck cancer (1 paper); liver cancer (1); oral cancer (1); yolk sac tumour (1).